Y_RNA (Y RNA )
Gene: Miscellaneous RNA gene on chromosome 19 (56,105,416 to 56,105,510, forward strand). Ensembl gene ENSG00000223060.
Homologues: Orthologues: chimpanzee Y_RNA (98% identical). Paralogues in human: RNY3P1 (85% identical), Y_RNA (85% identical), RNY3 (84% identical), Y_RNA (84% identical), Y_RNA (83% identical), RNY3P14 (82% identical), Y_RNA (82% identical), Y_RNA (81% identical), RNY3P16 (80% identical), RNY3P7 (80% identical), Y_RNA (80% identical), RNY3P13 (79% identical), and 90 more.